GDNF (glial cell derived neurotrophic factor)
Diseases named in the same sentence as GDNF in open-access papers (continued):
Sharing a sentence is not in itself a finding about the gene and the disease.
breast carcinoma (20 papers, 2010 to 2026). "Using an unbiased genomics approach to uncover membrane-localized tumor-associated antigens (TAAs), we have identified glial cell line derived neurotrophic factor (GDNF) family receptor α 1 (GFRA1) as a breast cancer TAA." (PMID 29796165, 2018). "On the one hand, GFRα1 was identified as a target protein of ST3 beta-galactoside alpha-2,3-sialyltransferase 1 (ST3GAL1), which regulates the GDNF/GFRα1/RET pathway in breast cancer cells by mediating O-linked sialylation of GFRα1 and facilitating its interaction with RET." (PMID 35582425, 2022). "For breast cancer, KNTc-gD:GDNF retargeted GFRα1 by replacing the gD signal peptide and HVEM-binding domain with pre-pro-GDNF and deleting aa 38 to prevent nectin-1 binding." (PMID 41403403, 2026). "Taken together, these data suggest a role for RET expression and GDNF-mediated transcriptional programs in breast cancer disease progression, particularly in the aggressive Luminal B subtype." (PMID 36918928, 2023). "Research on the transcriptional effects of GDNF treatment in breast cancer models is extremely limited." (PMID 36918928, 2023). "The essential role of the GFRα family proteins in RET-mediated signal transduction has been recapitulated in breast cancer cell lines, with GFRα1 expression a limiting factor for GDNF-mediated signal activation in multiple in vitro studies." (PMID 36918928, 2023). "In other words, GDNF-mediated GFR/RET activation promotes breast cancer proliferation and migration." (PMID 35582425, 2022). "In Morandi’s study, GDNF-RET signaling was established as a rational therapeutic target to combat or delay the onset of aromatase inhibitor resistance in breast cancer." (PMID 35311096, 2022). "In turn, GDNF induced transcription of ST3GAL1 through AKT/Sp1, revealing a positive feedback loop between ST3GAL1 and GDNF/GFRA1 signaling in breast cancer cells." (PMID 33921986, 2021). "Extensive in vitro data unequivocally demonstrate that in breast cancer cell lines, GDNF promotes cell migration and survival in an RET-dependent manner, rendering cells insensitive to anticancer drugs targeting EsR or aromatase." (PMID 32993133, 2020). "Here we report the design of a fully retargeted oHSV for preferential infection of breast cancer cells through virus recognition of GFRα1, the cellular receptor for glial cell-derived neurotrophic factor (GDNF)." (PMID 33233403, 2020). "In case of glioma or breast cancers, the GDNF-Ret signaling pathway can be blocked by GAS1 (growth arrest-specific 1) or by some Ret kinase inhibitors leading to the impairment of tumor growth." (PMID 32252363, 2020). "In this study, we have used genomic tools to dissect how the GDNF-RET signaling pathway becomes activated in breast cancer cells to promote resistance to endocrine therapies." (PMID 29608602, 2018). "Recognizing these important advantages we used PRO-seq to map the temporal dynamics of changes in RNA polymerase in response to GDNF treatment in MCF-7 breast cancer cells." (PMID 29614078, 2018). "We suggest that RET-mediated endocrine resistance occurs when ER+ breast cancer cells express the RET ligand GDNF." (PMID 29608602, 2018). "A careful examination of the GDNF expression distribution in TCGA breast cancers revealed a long tail, indicating high GDNF expression in a subset of cases in the TCGA dataset." (PMID 29608602, 2018). "In this study, we demonstrate that NVP-AST487 and NVP-BBT594 have comparable potencies as inhibitors of GDNF-induced RET signaling in ER+ breast cancer cells in vitro." (PMID 27602955, 2016). "Accordingly, the combination of the AI letrozole with the RET inhibitor NVP-BBT594 is more effective at suppressing GDNF-induced proliferation of RET+ ER+ breast cancer cells than either monotherapy." (PMID 27602955, 2016). "We have demonstrated previously that increased GDNF/RET signaling in ER+ breast cancers promotes AI resistance." (PMID 27602955, 2016).
breast carcinoma (continued). "We examined the breast cancer cell lines for Ret-mediated motility in response to GDNF, which activates Ret, as shown by an increase in its phospho-tyrosine content (pY)." (PMID 23868506, 2013). "A recent study has biochemically provided evidence that c-RET/GDNF signaling promotes proliferation of human breast carcinoma cells." (PMID 20422010, 2010). "Further studies are needed to determine the prognostic impact of these inhibitors in GDNF-RET-EGR1 expressing breast cancer and whether these inhibitors should be used alone or in combination with current endocrine therapies." (PMID 36765275, 2023). "Previous studies have suggested that GDNF/RET tyrosine kinase activates mitogen-activated protein kinase (MAPK) signaling components leading to endocrine resistant ERα+ breast cancer by promoting cell survival and proliferation that persists in the presence of endocrine therapies." (PMID 36765275, 2023). "At least in breast cancer cells, inflammatory mediators may upregulate GDNF expression, thus indirectly triggering RET signaling." (PMID 32993133, 2020). "Indeed, GDNF expression was detectible in only 565 of 1,177 primary breast cancers (48%) analyzed by TCGA." (PMID 29608602, 2018). "Another possibility is that GDNF expression in tumors may be initiated by pro-inflammatory cytokines, such as tumor necrosis factor alpha (TNFα), to be transcribed in breast cancer cells." (PMID 29608602, 2018). "To extend this hypothesis to primary breast cancers, we sought to determine whether GDNF expression is normally low, such that it might limit RET pathway activation in most ER+ breast cancers." (PMID 29608602, 2018). "Activation of SRF causes breast cancer cells to switch the active state of a bi-stable feedback loop, by transcriptionally repressing ERα and activating the transcription factor EGR1, which in turn leads to the secondary activation of GDNF." (PMID 29614078, 2018). "In addition, the stimulation of GFRα1-positive breast cancer cells with GDNF has been previously demonstrated to enhance cell proliferation and survival in vivo." (PMID 25120606, 2014). "Silencing of ST3GAL1 decreased GDNF-induced phosphorylation of RET, AKT and ERα, and reduced GDNF-mediated breast cancer cell proliferation." (PMID 33921986, 2021). "Based on this score, we conservatively estimate that, of 925 ER+ breast cancer patients in the TCGA dataset, 122 have high expression of at least one of the RET ligands (13%), 57 of which had high levels of GDNF." (PMID 29608602, 2018). "Both GDNF and IL6 stimulate migration of breast cancer cell lines and in vivo inhibition of Ret significantly decreases tumour outgrowth and the metastatic potential of an ER+ model." (PMID 23868506, 2013). "In these experiments it is important to note that there was no exogenous GDNF treatment indicating that in an in vivo setting RET signaling is active in these ER+ breast cancer xenografts." (PMID 27602955, 2016). "Four known biomarkers (CHEK2 in both plasma and urine, CDKN1B, PCNA, and THBS1) were identified as false positives (red) in our breast cancer list, and seven (KRAS, GDNF in both breastmilk and plasma, MYCL1 in both blood and serum, CD40LG, CGA, CTAG1A, ERCC6, and HRAS) in our lung cancer list." (PMID 25379168, 2014). "Thus, we propose that ER+ breast cancer cells are intrinsically ‘poised’ for RET-mediated endocrine resistance by the activation of RET cell-surface receptors, but lack expression of the ligand GDNF." (PMID 29608602, 2018). "Interestingly, while GDNF expression is regulated by estrogens in the brain microenvironment to serve neuroprotective functions, to our knowledge this effect has not been recapitulated in breast cancer models." (PMID 36918928, 2023).
epilepsy (18 papers, 2015 to 2025). A brain disorder characterized by episodes of abnormally increased neuronal discharge resulting in transient episodes of sensory or motor neurological dysfunction, or psychic dysfunction. "Further studies will focus on the effectiveness of AAV-Syn-BDNF-eGFP and AAV-Syn-GDNF-eGFP as therapeutic agents in provoking seizure activity in mutant mice with a genetic predisposition to epilepsy." (PMID 36009102, 2022). "Extensive preclinical evidence supports the anti-seizure efficacy of GDNF in animal epilepsy models." (PMID 41516142, 2025). "After adjusting for age and gender, multiple linear regression analysis demonstrated that both 5-HT and GDNF were independent factors affecting SDS score among all 107 epilepsy patients (Beta = −0.345, p < 0.001; Beta = −0.228, p = 0.042, respectively)." (PMID 39474368, 2024). "In particular, in the rat models of epilepsy, GDNF delivered by various routes exhibited a beneficial effect by suppressing seizures and/or reducing their frequency." (PMID 38069144, 2023). "We observed similar alterations by GDNF in human hippocampal slices resected from epilepsy patients." (PMID 36361981, 2022). "Previous studies from our and other groups have shown an anti-seizure effect of GDNF when either delivered or over-expressed in epileptic tissue in animal models of epilepsy." (PMID 36361981, 2022). "GDNF is a particularly interesting candidate for epilepsy as it is physiologically found within the temporal lobe, is upregulated in response to seizure activity, and local delivery can reduce seizures in animal models." (PMID 34366802, 2021). "Another investigation explored the delivery of GDNF to the hippocampus of rats with epilepsy via an implantable cell encapsulation mechanism." (PMID 33815100, 2021). "For example, it showed that the KO of miR-451 alleviated the behavior deficits and apoptosis of hippocampus in mice with KA-induced epilepsy by upregulating GDNF level." (PMID 33510702, 2020). "The beneficial effects of GDNF-releasing cells have also been observed in other epilepsy models." (PMID 40839114, 2025). "In the rat pilocarpine SE model, for example, encapsulated GDNF-releasing cells were implanted bilaterally during the chronic stage of epilepsy, resulting in a significant reduction in SRS frequency, prevention of hippocampal volume loss, and decreased neurodegeneration." (PMID 40839114, 2025). "Similarly, encapsulated GDNF-secreting cells have demonstrated efficacy in multiple epilepsy models, particularly in chronic stages, with sustained GDNF release and neuroprotection." (PMID 40839114, 2025). "GDNF and its receptor are expressed in the pyramidal and granule cells of the hippocampus, and a link has been found between the neurotrophic factor levels and epilepsy, since locally increasing GDNF levels in the temporal lobe can suppress epileptic activity." (PMID 40642294, 2025). "We also aimed to explore the potential of lacrimal GDNF as a biomarker of epilepsy." (PMID 38069144, 2023). "The involvement of GDNF in the pathogenesis of epilepsy has been studied using animal models." (PMID 38069144, 2023). "There are several additional hypothetical mechanisms for how increased extracellular levels of GDNF may suppress seizures in models of chronic epilepsy." (PMID 36361981, 2022). "Next, considering the possible value in treating drug-resistant epilepsies with GDNF gene therapy, we asked whether the effect of GDNF on inhibitory transmission would also be present in the human epileptic brain." (PMID 36361981, 2022). "Evidently, alterations in expression of neurotrophic factors, such as BDNF and GDNF, have been observed in epilepsy and neuropsychiatric disorders, and aberrant expression of these factors may be amenable to stem cell therapy." (PMID 33815100, 2021). "Initial studies evaluated the potential of GDNF in pre-clinical models of epilepsy." (PMID 34366802, 2021).
epilepsy (continued). "In the presence of IL-1β and TNF-α, astrocytes release NGF, BDNF, and glial-cell derived neurotrophic factor (GDNF), which could explain why cytokines released in the brain cause neurodegeneration and neurogenesis in epilepsy." (PMID 32992620, 2020). "Additionally, we investigated whether these cells could serve as effective delivery systems for GDNF, which has shown seizure-suppressing properties in various epilepsy models." (PMID 40839114, 2025). "Of note, GDNF may also play a role in epilepsy-induced neuropsychiatric compilations." (PMID 33815100, 2021). "Logistic regression models demonstrated that the probability of FE can be evaluated using GDNF in LF and BDNF in BS; that of MDD using GDNF in LF and cortisol and TNF-α in BS; and that of epilepsy with MDD using GDNF in LF and TNF-α and BDNF in BS." (PMID 38069144, 2023). "Though not yet deeply explored, the therapeutic potential of GDNF for hippocampus-related neurological disorders (including epilepsy) is regarded as fairly high." (PMID 38069144, 2023). "BDNF and CNTF levels did not depend on the etiology of epilepsy, while GDNF level was higher in two PWE subgroups as compared with the “trauma” subgroup." (PMID 36142325, 2022). "In addition, the upregulation of GDNF and GFRA1 has been reported in stroke (ischemia) and epilepsy (seizure disorder)." (PMID 29617307, 2018). "Preclinical studies have shown that seizures can be suppressed by the overexpression of BDNF or GDNF in the hippocampus or cerebral cortex in animal models of epilepsy, suggesting that the lack of these NTFs may play a role in epileptogenesis." (PMID 39474368, 2024). "However, similar to the previous data, the changes in levels of GDNF in LF and BDNF and cortisol in BS, assessed in the present study, did not depend on the etiology of epilepsy and were related to epilepsy in general, independent of its etiology." (PMID 38069144, 2023).
glaucoma (18 papers, 2012 to 2025). Increased pressure in the eyeball due to obstruction of the outflow of aqueous humor. "BDNF-mediated, CNTF-mediated, NGF-mediated, and GDNF-mediated neuroprotection in glaucoma has great potential, but retinal delivery is challenging, and adverse effects must be addressed." (PMID 38132117, 2023). "Several research teams have evaluated the glial cell line-derived neurotrophic factor (GDNF)—loaded PLGA NPs for the neuroprotection of glaucoma." (PMID 36899348, 2023). "For instance, PLGA microspheres containing glial cell line-derived neurotrophic factor (GDNF) were developed to promote retinal ganglion cell survival, expressing both GDNF and its receptor, in a rat model of glaucoma." (PMID 37376219, 2023). "These miRNAs are connected with proliferation, apoptosis, and cardiac injury as well as transforming growth factor-β1 (TGF-β1) and glial cell line-derived neurotrophic factor (GDNF) regulation during glaucoma, asthma and obesity." (PMID 32283635, 2020). "Taken together, GDNF exerts neuroprotective effects directly and/or indirectly via glia, and GDNF holds strong therapeutic potential for retinal diseases especially retinitis pigmentosa and glaucoma." (PMID 27657046, 2016). "Increased expression of GDNF mRNA induced by activated microglia indicates that neuroprotective effect may be a consequence of the secondary response of Müller cells in glaucoma." (PMID 34952606, 2021). "However, the best part of their findings appears when the same GDNF MP were administered to what can be considered a “chronic” model of glaucoma." (PMID 31991667, 2020). "Moreover, GDNF treatments, specifically intravitreal injection of microspheres containing GDNF, protect RGCs in glaucoma animal models." (PMID 32218163, 2020). "Besides these neurotrophins, ciliary nerve trophic factor (CNTF) and glial cell-derived neurotrophic factor (GDNF) are often cited as potent neuroprotective agents in glaucoma." (PMID 31484425, 2019). "A single IVT injection of the glial cell-derived neurotrophic factor (GDNF) encapsulated in vitamin E/PLGA microspheres was found to protect RGCs in animal models of glaucoma for up to 11 weeks by providing the sustained controlled release of GDNF in a controlled fashion for up to 6 months." (PMID 29098325, 2018). "Microsphere-delivery of GDNF also stimulated survival of RGCs in an experimental glaucoma model." (PMID 27657046, 2016). "Several NTFs have been reported to be associated with glaucoma, including nerve growth factor (NGF), brain-derived neurotrophic factor (BDNF), ciliary neurotrophic factor (CNTF), fibroblast growth factor 2 (bFGF), glial-derived neurotrophic factor (GDNF), and neurturin." (PMID 36579616, 2022). "Neurotrophic factors such as nerve growth factor (NGF), BDNF, CNTF, FGF-2, glial cell-line-derived neurotrophic factor (GDNF), neurturin (NRTN), and neuritin are particularly relevant to glaucoma." (PMID 39458902, 2024). "GDNF/Vitamin E Poly(lactide-co-glycolide) (PLGA) microsphere injections in a glaucoma animal model notably improved RGC longevity over 11 weeks, surpassing GDNF, Vitamin E, and mere microspheres." (PMID 38132117, 2023). "In a spontaneous glaucoma model, DBA/2J mice, intravitreal injection of microspheres containing GDNF significantly increased long-term RGC survival." (PMID 27657046, 2016). "Extremely low amounts of GDNF released from their MS (0.8 pg/day) achieved a therapeutic effect on the retina, protecting RGC in a glaucoma model (damage caused by increasing the IOP in a non-aggressive manner)." (PMID 31991667, 2020). "Glial- derived neurotrophic factor (GDNF), a growth factor shown to exert long-term neuroprotection when secreted from Müller cells in a rat model of retinitis pigmentosa and increase long-term ganglion cell survival in glaucoma was also strongly up-regulated at all times post-ESMV administration." (PMID 23226281, 2012).